MFN2 (mitofusin 2)
Diseases named in the same sentence as MFN2 in open-access papers (continued):
Sharing a sentence is not in itself a finding about the gene and the disease.
cardiac hypertrophy (continued). "Mfn2 expression is decreased in various rat models of cardiac hypertrophy, including MI and TAC." (PMID 34026850, 2021). "The main mitochondrial fusion protein Mfn2 was downregulated in cardiac hypertrophy." (PMID 33637715, 2021). "Additionally, MFN1 levels have been found to decrease in myocardial hypertrophy, while MFN2 levels increase under oxidative stress, however, MFN2 levels in the late stage after myocardial infarction and diabetis late stageare significantly reduced." (PMID 34660720, 2021). "Interestingly, the effects of Mfn2 overexpression ameliorated Ang II-induced cardiac hypertrophy via facilitating Parkin translocation and phosphorylation, triggering mitophagy." (PMID 34026850, 2021). "Although the functions of Mfn2 in cardiac hypertrophy and heart failure are far more complex than what we have yet known, enhancing Mfn2 function or upregulating expression may be useful as a therapeutic strategy for cardiac hypertrophy and heart failure." (PMID 34026850, 2021). "On the other hand, overexpression of cardiac Mfn2 could attenuate angiotensin II-induced myocardial hypertrophy." (PMID 33392184, 2020). "Our future work will focus on whether miR-195-5p regulates the integrity and function of the mitochondria by targeting MFN2 in cardiac hypertrophy." (PMID 31341888, 2019). "Taken together, our study indicates that miR-195-5p promotes cardiac hypertrophy via targeting MFN2 and FBXW7 and may provide promising therapeutic strategies for interfering cardiac hypertrophy." (PMID 31341888, 2019). "In addition, Mfn2 is involved in mitochondrial fusion, expression of which is down-regulated in various rat models of cardiac hypertrophy, including spontaneously hypertensive rats, transverse aortic banding, and MI." (PMID 31031629, 2019). "The effect of MFN2 in cardiac hypertrophy was further elucidated using mice with cardiac-specific MFN2 knockout, where a loss of tethering to the ER may cause impaired Ca2+ signalling or enhanced ROS production." (PMID 25987420, 2015). "Moreover, MFN2 downregulation was observed in a rodent model of cardiac hypertrophy, and MFN2 upregulation could constrain myocardial hypertrophy." (PMID 39594472, 2024). "Therefore, myocardial hypertrophy can be inhibited by up-regulation of MFN2 expression." (PMID 35783853, 2022). "According to them, miR-17-5p targets mitofusin 2 (MFN2) to activate the PI3K/AKT/mTOR axis, thus reducing autophagy and promoting pathological cardiac hypertrophy." (PMID 38256030, 2024). "Recently, a study showed that compared to MFN1/MFN2 cardiac knockout or DRP1 cardiac knockout mice, MFN1/MFN2/DRP1 cardiac triple knockout mice survived longer and manifested a unique pathological form of cardiac hypertrophy." (PMID 35783853, 2022). "Both in vitro and in vivo models of cardiac hypertrophy and HF decreased OPA1 and Mfn2 expression and increased mitochondrial fragmentation." (PMID 30131726, 2018). "A study found that 8 weeks of treadmill exercise reduced mitochondrial fusion protein (mitofusin 2, MFN2) expression in the hearts of hypertrophic mice and suppressed the downstream NLRP3/caspase-1/IL-1β signaling pathway, thereby alleviating myocardial hypertrophy and improving cardiac function." (PMID 39834360, 2024). "Under basal conditions, cardiac-specific MFN2 knockout mice show cardiac hypertrophy and moderate diastolic dysfunction, but no systolic dysfunction." (PMID 33240899, 2020). "Another related study utilizing transverseaortic constriction (TAC) induced cardiac hypertrophy model, as well as AngII-induced HCM model in rats, showed that the expression of miR-5-17p inmyocardial tissue was up-regulated, and the expression of Mfn2 protein wasdecreased." (PMID 39077079, 2023). "However, another study shows that cardiac deletion of Mfn1 and Mfn2 in mice is no sign of cardiac hypertrophy at 8–10 weeks, with normal left ventricular volume and normal contractile performance." (PMID 34026850, 2021).
cardiac hypertrophy (continued). "In addition, it has been recently demonstrated that miR-17-5p targets Mfn2 (Mitofusin 2), a mitochondrial fusion protein that plays a role in balancing autophagy and inhibits its expression, activating the PI3K/AKT/mTOR pathway and suppressing autophagy to promote cardiac hypertrophy." (PMID 36230953, 2022).
diabetes (50 papers, 2011 to 2025). "The PGC-1α pathway regulates MFN2, whose deficiency has been associated with IR and diabetes, followed by PGC-1α deficiency as well." (PMID 36674144, 2023). "In diabetes, the expression (protein and gene) of Mfn2, one of the major proteins associated with the fusion of outer membrane, is downregulated, and mitochondrial fragmentation is increased." (PMID 37415667, 2023). "Altered expression of MFN1 and MFN2 has been implicated by several studies for abnormal mitochondrial metabolism and the development of diabetes." (PMID 33924849, 2021). "MFN2 is also implicated in many other diseases such as cancer, cardiomyopathies, diabetes and Alzheimer's disease." (PMID 32788232, 2020). "Under nutrient excess with glucose and high fatty acid, the levels of dynamic fusion proteins (Mfn1/Mfn2) were found to be lower in both diabetes-susceptible cybrid B4 and diabetes-resistant D4 cells." (PMID 32849261, 2020). "Changes in Mfn2 activity are linked to various human mitochondria-associated diseases, such as Charcot-Marie-Tooth type 2A neuropathy, diabetes, and cardiovascular diseases." (PMID 23755235, 2013). "In addition, the partial abolishment of MFN2 expression led to abnormal mitochondrial metabolism in vitro, which is a key risk factor in the development of diabetes." (PMID 33924849, 2021). "Finally, MFN2 is also linked to diabetes, an aspect of crucial importance in our present society." (PMID 31156446, 2019). "In diabetes, Mfn2 is downregulated, and its activity is inhibited, leading to fragmented mitochondria with partial crystolysis and poor respiration." (PMID 40650203, 2025). "This has been attributed to reduced mitofusin 2 (Mfn2) protein expression, which impairs mitochondrial fusion in diabetes." (PMID 38602042, 2024). "Similar phenomenon was observed in diabetic mice; overexpression of sirtuin 1 (a deacetylase) ameliorated diabetes-induced inhibition of retinal Mfn2 and facilitated the removal of the damaged mitochondria." (PMID 37415667, 2023). "Activation of DNA methylation machinery in diabetes downregulates retinal Mfn2 gene transcripts, and here we show that Sirt1 inhibition leaves it hyperacetylated with reduction in its GTPase activity." (PMID 37415667, 2023). "Similar phenomenon is observed in the retina of diabetic mice where overexpression of Sirt1 ameliorates diabetes-induced decrease in the GTPase activity of Mfn2, and the formation of autophagosomes for the removal of the damaged mitochondria." (PMID 37415667, 2023). "In diabetes, while mitochondrial fusion protein (Mfn2) is decreased, fission protein (Drp1) is increased, resulting in fragmented mitochondria." (PMID 37175784, 2023). "Our results demonstrate that GTPase activity of Mfn2 is decreased in diabetes and its acetylation is increased, resulting in the fragmented mitochondria." (PMID 37415667, 2023). "As demonstrated by our present study, diabetes causes a dysregulation in the expression of mitochondria-associated proteins in the ventricular myocardium, including PGC-1 α, Mn-SOD, TFAM, and MFN2." (PMID 36139819, 2022). "Mitofusin-2 (Mfn2) play a critical role in diabetes through promoting glucose oxidation, insulin sensitivity, mitochondria and endoplasmic reticulum function." (PMID 35597446, 2022). "Significant increases in p-DRP1 and decreases in MFN2 levels were noticed in all diabetic groups, indicating that mitochondrial fission dominated over fusion in diabetes." (PMID 36008962, 2022). "Both basic and clinical studies show that Mfn2 plays an important role in biogenesis and metabolism in diabetes." (PMID 35976278, 2022). "This study is novel in two ways; first, previous studies on Mfn2 mostly focused on cardiovascular and cerebrovascular diseases, and diabetes, etc., and there is little research on Mfn2 and pelvic floor diseases." (PMID 35627214, 2022).
diabetes (continued). "Re-institution of good glycemic control, soon after induction of diabetes in rats (GC group), however, protected hypermethylation of Mfn2 and Mlh1 promoter DNA, and along with the binding of Dnmt1, prevented decrease in their gene transcripts." (PMID 32313015, 2020). "In particular, post hoc analysis indicated that diabetes significantly decreased MFN2 protein levels in male rats (Bonferroni post hoc analysis, p < 0.05)." (PMID 29351809, 2018). "There is growing evidence showing that MFN2 is involved in a range of pathologies, including tumorigenesis, diabetes, cardiovascular disease and so on." (PMID 30498519, 2018). "To examine the causal role of mitochondrial dynamics in insulin resistance relevant to mtDNA variants, we established cybrid cell harboring diabetes mellitus- (DM-) susceptible mtDNA haplogroup B4 (thereafter DM cybrid) and overexpressed Mfn1, Mfn2, Drp1, and Fis1 in cybrid B4." (PMID 30363990, 2018). "Our observations are consistent with another study, which demonstrated reduced MFN2 expression in retina of diabetic rats and human donors with duration of diabetes ≥ 10 years." (PMID 29326655, 2017). "Furthermore, aberrant Mfn2 expression has been reported in metabolic disorders, including type 2 diabetes mellitus and insulin resistance, for which Exenatide and GLP-1R agonists are effective in treatments." (PMID 38627765, 2024). "Furthermore, Sirt1 overexpressing mouse model, the model which is protected from the development of diabetic retinopathy and retinal mitochondrial damage, is also protected from diabetes-induced increase in Mfn2 acetylation and decrease in its GTPase activity." (PMID 37415667, 2023). "In summary, OPA1, MFN1, MFN2 mRNA and protein expression analysis shows that mitochondrial fusion dysfunction occurs during the development of diabetes, resulting in abnormal mitochondrial morphology, and ShenQiWan can alleviate the renal injury by stabilizing the mitochondrial fusion process." (PMID 38026991, 2023). "Similarly, the RBP HuD, known to regulate MFN2, is downregulated in diabetes contributing to mitochondrial dysfunction." (PMID 37719978, 2023). "As expression of MFN1 and MFN2 is reduced in cardiomyocytes and skeletal muscle of patients with diabetes, respectively, activators of Mfn1/2 may have additional benefits beyond improving β-cell function." (PMID 35487893, 2022). "To determine the mitochondrial function in the three groups, we evaluated the expression of mitochondria-associated proteins of ventricular tissue and found that the expression levels of PGC1-α, Mn-SOD, TFAM, and MFN2 showed a decreasing trend in the diabetes group compared to the control group." (PMID 36139819, 2022). "As such, it may simply be a coincidence that the peripheral neuropathy appeared around the same time as the patient’s diabetes, and that MFN2 dysfunction was responsible." (PMID 38274408, 2021). "Furthermore, insulin administration reverses mitochondrial structural changes in diabetics, upregulates Mfn2 expression, and induces mitochondrial biogenesis (Pawlikowska, Gajkowska & Orzechowski, 2007)." (PMID 29068134, 2018). "Two-way ANOVA revealed a significant effect of diabetes (p < 0.05) on MFN2 levels." (PMID 29351809, 2018). "Mitofusin 2 (Mfn2), mitochondrial outer membrane protein which is involved in rearrangement of these organelles, was first described in pathology of hypertension and diabetes, and more recently much attention is paid to its functions in Charcot-Marie-Tooth type 2A neuropathy (CMT2A)." (PMID 26230519, 2015). "However, overexpression of Sirt1 attenuated diabetes-induced decrease in Mfn2 activity." (PMID 37415667, 2023). "Therefore, changes in Mfn2 observed in oxidative stress conditions could account for the altered lipid metabolism found in the metabolic syndrome or diabetes." (PMID 30060502, 2018).
diabetes (continued). "To address whether mtDYN plays a causal role in regulating cellular IR and serves as a potential therapeutic target, we have bidirectionally manipulated the expression of dynamic proteins, including MFN1, MFN2, DRP1, and FIS1 in cybrid cell harboring diabetes-susceptible haplogroup B4." (PMID 30363990, 2018). "LncRNAs can regulate gene expression by epigenetic modifications, and Mfn2 promoter DNA is hypermethylated in diabetes; the role of MALAT1 in Mfn2 DNA methylation was evaluated." (PMID 40650203, 2025). "We have previously shown that, in diabetes, MALAT1 is upregulated in the retina and its capillary cells, Mfn2 promoter DNA is hypermethylated, and mitochondrial fission is increased." (PMID 40650203, 2025). "Nicotinamide riboside promotes Mfn2-mediated mitochondrial fusion via the SIRT2-PGC1α-PPARα pathway, reduces diabetes-induced cardiomyocyte apoptosis, and prevents diabetes-induced cardiac insufficiency." (PMID 37670891, 2023). "In addition, diabetes decreases autophagosome formation and mitophagy in the retinal mitochondria, and Sirt1 overexpression ameliorates this, further strengthening the role of Mfn2 activation in the mitochondrial dynamic and removal of the damaged mitochondria in diabetic retinopathy." (PMID 37415667, 2023). "The literature shows that both diabetes and an HFD can impair MFF and MFN2 expression in other tissues, such as cardiac tissue in male rats and skeletal muscles in diabetic patients." (PMID 37892483, 2023). "In conclusion, the upregulation of MALAT1 in diabetes facilitates Mfn2 promoter DNA hypermethylation in retinal vascular and nonvascular cells, leading to its suppression and the accumulation of the fragmented/damaged mitochondria." (PMID 40650203, 2025). "At the current time, studies on Mfn2 are mostly focused on cardiovascular and cerebrovascular diseases, diabetes, and cancer, and there is a lack of research on the relationship between Mfn2 and POP." (PMID 35627214, 2022). "In some cases, even though Mfn2 level was not changed in response to diabetes, the ratio of Mfn2 to Drp1 was decreased and was prevented by exercise." (PMID 33339212, 2020). "The upregulation of MALAT1 in diabetes in both vascular and nonvascular cells facilitates the hypermethylation of Mfn2, and this results in Mfn2 gene suppression and the inhibition of its GTPase activity, leading to the accumulation of fragmented/damaged mitochondria." (PMID 40650203, 2025). "Collectively, our study demonstrated that cordycepin could be a potential cardioprotective agent for myocardial I/R injury in diabetes, and established a novel mechanism by which upregulated AMPK/Mfn2-dependent mitochondrial fusion contributes to the cardioprotective role of cordycepin." (PMID 34744731, 2021).
Insulin resistance (45 papers, 2013 to 2026). Increased resistance towards insulin, that is, diminished effectiveness of insulin in reducing blood glucose levels. "MFN2 deficiency was associated with the development of ER stress, elevated cellular content of hydrogen peroxide, and insulin resistance." (PMID 39519269, 2024). "Liver-specific knockout of Mfn2 causes excessive mitochondrial fission, reduces insulin signal transduction in muscle and liver tissues, and induces susceptibility to insulin resistance (IR)." (PMID 38542170, 2024). "Conversely, MFN2 liver ablation in mice was associated with high glucose production and insulin resistance and reduced autophagy." (PMID 31974316, 2020). "Mfn2 deficiency is associated with enhanced hydrogen peroxide concentrations, altered reactive oxygen species regulation, insulin resistance, and endoplasmic reticulum stress." (PMID 26942197, 2016). "Interestingly, increased oxidative stress and ER stress as well as activation of JNK was found in condition of MFN2 deficiency and the specific loss of Mfn2 in hepatocytes was associated with hepatic insulin resistance." (PMID 29538286, 2018). "Therefore MFN2 is implicated as a potential target for the treatment of insulin resistance and metabolic syndromes." (PMID 23815800, 2013). "Specifically, deletion of Mfn2 in all adipocytes or in brown adipocytes alone caused reduced expression of multiple oxidative phosphorylation subunits and impaired cold tolerance yet, paradoxically, both mouse lines were protected from systemic insulin resistance." (PMID 39739772, 2024). "FABP4 KD restored contractility, while Mfn2 overexpression improved mitochondrial function and alleviated insulin resistance." (PMID 40192565, 2025). "Correspondingly, animal models with partial gene knockout of Mfn2 in skeletal muscle showed impaired glucose tolerance and insulin resistance, while overexpression models displayed moderate muscle hypertrophy without pathological changes." (PMID 39655345, 2024). "MFN-2 is a key protein responsible for promoting mitochondrial fusion with its overexpression ameliorating PA-induced insulin resistance." (PMID 34136519, 2021). "Surprisingly, loss of Mfn2 in BAT protected high-fat diet-fed mice from hepatic steatosis and insulin resistance." (PMID 34114603, 2021). "First the expression level of Mfn2 affects the insulin signaling pathway; individuals with low Mfn2 expression in the liver are more likely to develop insulin resistance." (PMID 34604240, 2021). "Accordingly, MFN2 ablation protects against high-fat diet-induced insulin resistance in brown adipose tissue." (PMID 34869541, 2021). "Conversely, overexpression of Mfn2 improved high-fat diet (HFD)-induced hepatic insulin resistance in rats." (PMID 33339212, 2020). "By contrast, MFN2 overexpression ameliorated HFD-induced insulin resistance by targeting insulin signaling pathways." (PMID 32630236, 2020). "Disrupting MAM through silencing of Grp75, Mfn2, or inhibiting cyclophilin D increased expression of ER stress markers in hepatoma cells and contributed to the development of hepatic insulin resistance under conditions of SFA overload." (PMID 31540165, 2019). "Mfn2 ablation in the liver and skeletal muscle increased ER stress markers and promoted hyperlipidemia-induced insulin resistance." (PMID 31540165, 2019). "In agreement, overexpression of Mfn2 improved diet-induced hepatic insulin resistance and chemical chaperones ameliorated glucose tolerance and insulin signalling in liver-specific Mfn2 KO mice." (PMID 29538286, 2018). "Their results indicate that Mfn‐2 overexpression can also improve insulin resistance by attenuating the overactivation of the ROS‐JNK/p38MAPK pathway induced by NEFAs in cow hepatocytes." (PMID 29602237, 2018). "All these reports suggest that disruption of mitochondrial dynamics play a role in insulin resistance and type 2 diabetes with special emphasis on the role of Mfn2." (PMID 29538286, 2018).